CCK (cholecystokinin)
Diseases named in the same sentence as CCK in open-access papers (continued):
Sharing a sentence is not in itself a finding about the gene and the disease.
glioblastoma (3 papers, 2021 to 2025). The most malignant astrocytic tumor (WHO grade IV). "We initially confirmed glioblastoma (GBM) malignancy and therapeutic responses to CCK overexpression and IDH1 mutations in cerebral cortex and frontal cortex tissue samples." (PMID 41057875, 2025). "Glioblastoma cells (U-87MG) express both cholecystokinin (CCK) and CCK B receptors." (PMID 39063232, 2024).
glioma (3 papers, 2017 to 2024). A benign or malignant brain and spinal cord tumor that arises from glial cells (astrocytes, oligodendrocytes, ependymal cells). "CCK antagonists promote apoptosis in glioma cells by increasing caspase 3 activity, and the antagonist of the ETB receptor BQ788 inhibits the proliferation of oligodendroglioma cells and increases survival." (PMID 39063232, 2024). "First, the present study analysed intracellular signalling via CCK and leptin in rat C6 glioma cells." (PMID 32686770, 2020). "The following peptides, through their respective receptors, promote glioma progression (proliferation, migration, invasion, and angiogenesis): AMD, angiotensin II, GRP, bradykinin, CCK, endothelin, neuromedin B, neurotensin, and substance P." (PMID 39063232, 2024).
heart failure (3 papers, 2021 to 2025). Inability of the heart to pump blood at an adequate rate to meet tissue metabolic requirements. "In an animal model of myocardial infarction, the upregulation of CCK was correlated with markers of heart failure progression, such as BNP levels, left ventricular end-systolic diameter, ejection fraction, and shortening fraction." (PMID 36834796, 2023). "In clinical studies of heart failure patients, CCK levels predicted mortality in elderly women, suggesting an important role of CCK in cardiovascular risk assessment." (PMID 36834796, 2023). "The study found that CCK expression in the postinfarction heart failure (HF) group was higher than that in the sham group." (PMID 34497680, 2021). "Recent animal studies have shown that high expression of CCK can be seen in HF rat myocardial tissue, and the concentration of CCK in plasma of heart failure model rats is higher than that of the non-HF group." (PMID 34497680, 2021).
Hypercholesterolemia (3 papers, 2012 to 2025). An increased concentration of cholesterol in the blood. "It is highly possible that the age-related increase in plasma CCK is responsible for the increased bile release and hypercholesterolemia." (PMID 23300532, 2012). "This CCK-induced hypercholesterolemia might be clinically important." (PMID 23300532, 2012).
insomnia (3 papers, 2016 to 2024). A sleep disorder characterized by difficulty in falling asleep and/or remaining asleep. "In summary, treatment with MSZRD provided the benefits of sleep improvement and protection against gastrointestinal disorders in a rat model of insomnia, possibly through a mechanism related to Orexin-A and CCK-8." (PMID 32617111, 2020). "The present study observes the behavioral activities of the rat model of insomnia and the contents of orexin-A and CCK-8 in hypothalami to explore the action mechanism of Heweianshen decoction treating insomnia." (PMID 27688792, 2016). "The therapeutic effect of HAD on insomnia is partially attributed to the decreased expression of orexin-A and increased expression of CCK-8." (PMID 27688792, 2016). "The BNST GABAergic system played a role in sleep-wakefulness control, and reward-promoting cholecystokinin-BNST neurons received their dense inputs from the Me, which provided an essential mechanism underlying the emotional arousal regulation and the pathophysiology of insomnia." (PMID 38842948, 2024).
lung carcinoma (3 papers, 2017 to 2025). "Other studies also reported a role for CCK in promoting cell proliferation of lung cancer cells." (PMID 36599824, 2023).
morphine dependence (3 papers, 2012 to 2018). Strong dependence, both physiological and emotional, upon morphine. "Studies demonstrated that cholecystokinin (CCK) system involved in morphine dependence and withdrawal." (PMID 30147637, 2018). "In conclusion, we identified a difference between the role of the CCK1 and CCK2 receptor on the development of morphine dependence and an inhibitory effect of high-doses of exogenous CCK-8 on cellular morphine dependence." (PMID 22682150, 2012). "This system is useful for the study of the potential regulatory effects of exogenous CCK-8 on morphine dependence." (PMID 22682150, 2012). "We verified that endogenous CCK played an anti-opioid role and potentiated the development of morphine dependence via the CCK2 receptor." (PMID 22682150, 2012). "Recent studies have shown the involvement of the endogenous CCK system in physical and psychological morphine dependence." (PMID 22848639, 2012). "In this present study, we describe a distinct effect of exogenous CCK-8 on the development of morphine dependence in vitro." (PMID 22682150, 2012). "In summary, our study identifies a different role of CCK1 and CCK2 receptor in development of morphine dependence and an inhibitory effect of high-dose exogenous CCK-8 on the acquisition of naloxone-precipitated withdrawal-induced CPA." (PMID 22848639, 2012). "Cholecystokinin octapeptide (CCK-8), the most potent endogenous anti-opioid peptide, has been shown to regulate the processes of morphine dependence." (PMID 22682150, 2012). "Thus, we suggest a new interpretation in which exogenous CCK-8 affects the morphine dependence by regulating the process of learning and the expression of memory during conditioning." (PMID 22848639, 2012). "Therefore, L-364,718, a CCK1 receptor antagonist, and LY-288,513, a CCK2 receptor antagonist (0.01-10 μM), were utilised to examine endogenous CCK regulation of the development of morphine dependence in SH-SY5Y cells." (PMID 22682150, 2012). "In addition, this study provides the first evidence for the participation of the CCK1 receptor in the mechanism by which exogenous CCK-8 inhibits morphine dependence." (PMID 22682150, 2012). "Thus, CCK receptor subtypes that mediate the inhibitory effects of exogenous CCK-8 on morphine dependence remain to be determined." (PMID 22682150, 2012). "In addition, the subtypes of CCK receptor that mediate the function of CCK-8 on morphine dependence are also investigated." (PMID 22682150, 2012). "Additionally, CCK1 receptor significantly blocked the inhibitory effect of exogenous CCK-8 on morphine dependence, but CCK2 receptor appears to be necessary for low concentrations of endogenous CCK to potentiate morphine dependence." (PMID 30147637, 2018). "This study reveals the difference between exogenous CCK-8 and endogenous CCK effects on the development of morphine dependence, and provides the first evidence for the participation of the CCK1 receptor in the inhibitory effects of exogenous CCK-8 on morphine dependence." (PMID 22682150, 2012). "The role of CCK2 receptor in the process of exogenous CCK-8 regulation on morphine dependence can not be ruled out." (PMID 22682150, 2012).
Sepsis (3 papers, 2007 to 2021). Sepsis is defined as life-threatening organ dysfunction caused by a dysregulated host response to infection. "Taking in account the involvement of inducible nitric oxide synthase- (iNOS-) derived NO in the sepsis context, the present study was undertaken to investigate the role of CCK on iNOS expression in LPS-activated peritoneal macrophages." (PMID 25125801, 2014). "Based on these findings, CCK could be used as an adjuvant agent to modulate the inflammatory response and prevent systemic complications commonly found during sepsis." (PMID 25125801, 2014). "Baseline plasma concentrations of both CCK and PYY were not related to gender (P = 0.82), the APACHE II score on the study day (P = 0.40), serum creatinine (P = 0.28), the type of sedation, the use of inotropes or acid suppression, the presence of sepsis, or prior enteral nutrition." (PMID 18154642, 2007).
amyloid (2 papers, 2023 to 2025). "For example, in a recent study, a CCK analog effectively improved spatial learning and memory, reduced amyloid plaque load in the brain, enhanced synaptic plasticity in the hippocampus, and normalized synapse number and morphology in APP/PS1 mice." (PMID 40013092, 2025). "Whereas intraventricular injection of amyloid does not alter CCK mRNA levels in the hippocampus, and the number of CCK INs in CA1 (in SO) remained unchanged with intrahippocampal injection of amyloid, APP/PS1 mice feature a reduction of CB1R-expressing CCK interneurons in DG and CA1." (PMID 37841892, 2023).
Atrophy (2 papers, 2024 to 2025). Any weakening or degeneration, especially through lack of use. "We assume that CCK, released in the neocortex by CCK positive neurons in the EC, which is the earliest site of atrophy in dementia patients, is the key chemical for memory encoding, and reduced CCK leading to a deficiency in encoding recent memory or anterograde amnesia in AD patients." (PMID 38750512, 2024).
autonomic neuropathy (2 papers, 2009 to 2018). An inherited or acquired peripheral neuropathy affecting the autonomic nervous system. "In patients with oesophageal dysmotility the basal level of CCK tended to be higher (p = 0.051) and those with autonomic neuropathy had a higher area under the curve (AUC) of gastrin compared to normal subjects (p = 0.007)." (PMID 19243587, 2009). "Reduced postprandial secretion of oxytocin was found in patients with delayed gastric emptying, CCK secretion was increased in patients with oesophageal dysmotility, and gastrin secretion was increased in patients with autonomic neuropathy." (PMID 19243587, 2009). "In a previous study Glasbrenner found CCK to be elevated in plasma from patients with autonomic neuropathy." (PMID 19243587, 2009). "However, in patients with oesophageal dysmotility the basal concentration of CCK tended to be higher, and in patients with autonomic neuropathy the gastrin concentrations were increased compared to normal subjects." (PMID 19243587, 2009). "Although both oxytocin, CCK, gastrin, and vasopressin are involved in postprandial release and motility, the plasma concentrations of these hormones have not been thoroughly examined in relation to dysfunction in GI motility or autonomic neuropathy." (PMID 19243587, 2009). "The third mechanism is impaired cholecystokinin (CCK) secretion in jejunum and reduced sensitivity to CCK in T2DM, and the severity aggravates for the patients with autonomic neuropathy." (PMID 30555418, 2018). "Another study showed significantly lower CCK concentrations in diabetics without autonomic neuropathy compared to healthy controls." (PMID 19243587, 2009). "Earlier studies have reported increased CCK and gastrin concentrations in plasma from diabetics with autonomic neuropathy, whereas patients without neuropathy showed normal concentrations, irrespective of GI function." (PMID 19243587, 2009). "Neither was there any difference in the AUC between those with or without autonomic neuropathy (29502.5 [9377.3–65353.4] and 30536.7 [10605.1–56321.3] for oxytocin, respectively; p = 0.743; and 423.0 [274.2–661.0] and 305.1 [258.4–369.0] for CCK, respectively; p = 0.195)." (PMID 19243587, 2009).
colitis (2 papers, 2016 to 2023). Inflammation of the colon. "Thirty-seven (37 = 58.7%) of these DMRs associated with genes, but only 6 (16.2%) of those have been implicated in either colitis (PTPRF, ELTD1, and GDNF) or CRC (PTPRF, ELTD1, PDX1, CCK, and AGPAT1)." (PMID 27006956, 2016).
colorectal cancer (2 papers, 2016 to 2018). A primary or metastatic malignant neoplasm that affects the colon or rectum. "Moreover, OxA and cholecystokinin (CCK) inhibited the migration of colorectal cancer cell line, HT-29 mediated by heterodimerization of OX1R and CCK1R." (PMID 30319552, 2018).
dementia (2 papers, 2024). Loss of intellectual abilities interfering with an individual's social and occupational functions. "Although the physiological etiology of CCK in AD still needs to be further investigated, this study sheds light on a potential pharmaceutical candidate for AD and dementia." (PMID 38750512, 2024).
dependence (2 papers, 2012 to 2023). "Moreover, we provide the first piece of evidence that a CCK1 receptor antagonist can reverse the inhibitory effects of exogenous CCK-8 on morphine dependence." (PMID 22682150, 2012).
diabetic neuropathy (2 papers, 2020 to 2021). A chronic, pathological complication associated with diabetes mellitus, where nerve damages are incurred due to diabetic microvascular injury involving small blood vessels that supply these nerves, resulting in peripheral and/or autonomic nerve dysfunction. "Central cortical and spinal sensitization, impaired inhibitory pain modulation, altered pancreatic nociception along with pancreatic neuropathy and neuroplasticity, increased cholecystokinin, norepinephrine, and diabetic neuropathy have all been studied as other causes of pain." (PMID 33763317, 2021).
Dystroglycanopathies (2 papers, 2022 to 2024). "Dystroglycanopathies are also associated with ID, and dystroglycan has been identified as critical in the development of α2 enriched CCK-positive basket cell synapses." (PMID 35169261, 2022). "In this study, we sought to better understand how CCK+/CB1R+ IN synapse formation is affected in mouse models that more accurately reflect dystroglycanopathy, in which Dystroglycan function is more broadly affected throughout the CNS." (PMID 38179984, 2024). "Mice that model severe dystroglycanopathy due to forebrain deletion of Dag1 or Pomt2, which is required for Dystroglycan glycosylation, show significant impairment of CCK+/CB1R+ IN development." (PMID 38179984, 2024). "In contrast, CCK+/CB1R+ IN synaptic function and seizure susceptibility was normal in mice that model mild dystroglycanopathy due to partially reduced Dystroglycan glycosylation." (PMID 38179984, 2024). "Given the perturbed distribution of CCK+/CB1R+ IN axons in the hippocampus, we next wanted to determine whether the remaining CCK+/CB1R+ IN axons were capable of forming synapses in dystroglycanopathy models." (PMID 38179984, 2024). "We demonstrate that Dystroglycan is critical for the postnatal development of CCK+/CB1R+ interneuron axon targeting and synapse formation/function in the hippocampus of severe mouse models of dystroglycanopathy." (PMID 38179984, 2024). "However, the development and function of CCK+/CB1R+ INs has not been examined in mouse models that more broadly lack Dag1 throughout the CNS and thus more accurately reflect the neuropathology of dystroglycanopathy." (PMID 38179984, 2024).
Endotoxemia (2 papers, 2014 to 2025). "Our in vitro results confirmed the animal findings that CCK administration before the endotoxemia induction in a single pulse and near at the physiological levels exerts anti-inflammatory properties, reducing the iNOS expression and cytokines synthesis." (PMID 25125801, 2014). "Endotoxemia lowers circulating CCK levels, compromises intestinal barrier integrity, and exacerbates inflammation in the ileum and colon, suggesting that inflammation can impair CCK synthesis." (PMID 40723884, 2025).
Ewing sarcoma (2 papers, 2013 to 2015). A small round cell tumor that lacks morphologic, immunohistochemical, and electron microscopic evidence of neuroectodermal differentiation. "All together, these results consistently demonstrate that CCK is expressed and secreted at high levels in Ewing sarcoma." (PMID 26258070, 2015). "Regarding the functional relevance of CCK in Ewing sarcoma, it was shown that downregulation of CCK using a shRNA inducible system, inhibited cell proliferation in vitro and tumor growth in vivo." (PMID 26258070, 2015). "In summary, although high levels of CCK in Ewing sarcoma tumors were described more than two decades ago, research in this field has been scattered during the last years, and many questions remain unresolved." (PMID 26258070, 2015). "In agreement with this, a later study demonstrated the presence of proCCK in the supernatant of Ewing sarcoma cell lines in culture, indicating that CCK is actively secreted by Ewing sarcoma cells." (PMID 26258070, 2015). "One complete cDNA (GenBank sequence ID: AK300784) representing an alternative splicing form of the CCK mRNA was found in a cDNA library of a human neuronal epithelioma Ewing tumor cell line." (PMID 23724068, 2013). "CCK induces cell proliferation in various cancer cell lines and serves as an autocrine growth factor in Ewing tumor cells." (PMID 23724068, 2013). "In addition, CCK-rich culture media or exogenous CCK-8 was able to stimulate Ewing sarcoma cell proliferation in vitro, suggesting that CCK is an autocrine growth factor in Ewing sarcoma cells." (PMID 26258070, 2015). "The fact that CCK is highly expressed in Ewing sarcoma and the observation that it can act as an autocrine growth factor in vivo suggest that blocking this autocrine loop, for example, using CCK receptor antagonists, could be of therapeutic interest." (PMID 26258070, 2015). "This means that radiolabeled CCK or other compounds with high affinity for CCK receptors could be useful for diagnosis (i.e., imaging) and perhaps also for the treatment of Ewing sarcoma." (PMID 26258070, 2015). "Thus, EWS/FLI1 knockdown in A673 and SK-PN-DW Ewing sarcoma cell lines downregulated CCK mRNA levels, demonstrating that CCK expression is dependent on EWS/FLI1." (PMID 26258070, 2015). "To further confirm the potential antagonist function of CCKsv, we checked if CCKsv could inhibit Ewing tumor cell growth stimulated by CCK." (PMID 23724068, 2013). "Because treatment with a CCK antagonist inhibits proliferation of Ewing tumor cells, CCK antagonist could represent a new therapeutic approach in the management of Ewing's tumor patients." (PMID 23724068, 2013). "CCK is known to be important for Ewing tumor progression, further studies on the antagonistic functions of CCKsv and its derivatives could allow the formulation of new peptides for anticancer therapy." (PMID 23724068, 2013). "More than two decades ago, CCK was found to be specifically expressed in a group of human cancer cell lines that included Ewing sarcoma, neuroepithelioma and leiomyosarcomas, as opposed to other tumor cell lines derived from osteogenic sarcomas, rhabdomyosarcoma, melanoma, and SCLC." (PMID 26258070, 2015).
exocrine pancreatic insufficiency (2 papers, 2021). Inability of the exocrine pancreas to produce and secrete an adequate amount of digestive enzymes into the small intestine. "Furthermore, hypocalcemia itself can cause malabsorption by reducing cholecystokinin secretion, decreasing gall bladder emptying, and causing pancreatic insufficiency." (PMID 34194389, 2021). "Other situations that would favor a CCK analogue over fatty meal stimulation include gastroparesis and exocrine pancreatic insufficiency when high CCK levels are often noted because of low proteolytic enzymes." (PMID 33569543, 2021).
fatty liver disease (2 papers, 2023 to 2024). A reversible condition wherein large vacuoles of triglyceride fat accumulate in liver cells via the process of steatosis. "Endogenous CCK blood levels are elevated with the consumption of a high-fat diet, especially saturated fats that are associated with fatty liver disease." (PMID 36835036, 2023). "Supportive of the non-CCK-BR mechanism in hepatic steatosis includes our prior research showing that proglumide decreases hepatic steatosis by serving as a partial FXR agonist." (PMID 38252699, 2024).